SOX17 (SRY-box transcription factor 17)
Diseases named in the same sentence as SOX17 in open-access papers (continued):
Sharing a sentence is not in itself a finding about the gene and the disease.
endotoxemia (1 paper, 2019). "Endotoxemia upregulates Hypoxia inducible factor 1α, which in turn transcriptionally activates Sox17 expression." (PMID 31073164, 2019). "Here we show that the endothelial and hematopoietic developmental transcription factor Sox17 promotes endothelial regeneration in the endotoxemia model of endothelial injury." (PMID 31073164, 2019). "However, we cannot rule out the possibility that endotoxemia can activate multiple inflammatory pathways and release paracrine growth factors and cytokines, which may also contribute to the expression of Sox17." (PMID 31073164, 2019).
germinoma (1 paper, 2023). A malignant germ cell tumor arising in the central nervous system. "However, it has been widely accepted that germinoma is a prototype of all GCTs, by CSC markers of Oct4, Nanog, SOX17 (germinoma), SOX2 (infantile GCTs), and differentiation markers of PLAP and KIT (germinoma differentiation markers from ES cells, rare in intracranial none germinoma GCTs (NGGCTs))." (PMID 37370764, 2023).
Glucose intolerance (1 paper, 2014). Glucose intolerance (GI) can be defined as dysglycemia that comprises both prediabetes and diabetes. "Despite restoration of normal resting glucose and insulin levels, SOX17 expression did not reverse the glucose intolerance of Pdx1tTA/+ mice." (PMID 25144761, 2014).
Impaired glucose tolerance (1 paper, 2014). An abnormal resistance to glucose, i.e., a reduction in the ability to maintain glucose levels in the blood stream within normal limits following oral or intravenous administration of glucose. "This suggests that SOX17 expression can rescue impaired fasting glucose but does not rescue impaired glucose tolerance." (PMID 25144761, 2014).
iron deficiency (1 paper, 2023). "Considering the 48 h DFO treatments, iron deficiency increased SOX-17 protein level, and FKN reduced its level at both concentrations." (PMID 37175630, 2023). "After 48 h long iron deficiency, FKN in the presence of serum significantly reduced SOX-17 protein level." (PMID 37175630, 2023). "The mRNA expression of the endometrium receptivity-related genes, PR, SOX-17, CX3CR1, FKN, activin, follistatin, BMP2, as well as the examined cytokines and chemokines LIF, IL-6, and IL-1β, were significantly downregulated at DFO-induced iron deficiency in HEC-1A cells." (PMID 37175630, 2023). "After shorter iron deficiency, FKN increased the SOX-17 level, but after 48 h it was not capable to maintain SOX-17 protein synthesis." (PMID 37175630, 2023).
kidney injury (1 paper, 2025). Trauma to the kidney. "Abnormal IgA deposition induces ROS-related mechanical stress, upregulating SOX17 expression, which may promote recruitment of CD8+ T cells and other inflammatory cells, further amplifying immune-mediated kidney injury." (PMID 41155038, 2025).
Lewis lung carcinoma (1 paper, 2024). "Sex‐determining region Y‐related high‐mobility group box 17 protein (SOX17), a proangiogenic transcription factor, is specifically expressed in tumor endothelial cells (TECs) of implanted Lewis lung carcinoma." (PMID 39385307, 2024). "SOX17 deletion in TECs inhibited tumor angiogenesis in implanted murine Lewis lung carcinoma model." (PMID 39385307, 2024).
liver diseases (1 paper, 2023). "Besides, SOX17, SULT2A1, and BLVRA have potential roles to play in other liver diseases." (PMID 36777627, 2023).
metastatic cancer (1 paper, 2015). A carcinoma which has spread from the original site of growth to another anatomic site. "In CTCs, SOX17 was methylated in 34.5 % of patients with early BC, 45.8 % of patients with metastatic cancer, and one healthy woman, whereas in matched plasma cfDNA samples, SOX17 was methylated in 34.5 %, 40.7 %, and one of the corresponding individuals, respectively." (PMID 26453190, 2015).
multiple sclerosis (1 paper, 2021). A progressive autoimmune disorder affecting the central nervous system resulting in demyelination. "Sox17 is involved in oligodendrocytes survival in models of de-myelination and multiple sclerosis." (PMID 33669272, 2021).
nephrotic syndrome (1 paper, 2010). A collection of symptoms that include severe edema, proteinuria, and hypoalbuminemia; it is indicative of renal dysfunction. "The screening for SOX17 mutations was extended to 178 individuals with sporadic VUR and in 305 controls consisting of 135 children with nephrotic syndrome, 88 normal subjects without a history of urinary infection who were not further characterized, and 82 cord blood samples (610 chromosomes)." (PMID 20960469, 2010).
Obesity (1 paper, 2022). Accumulation of substantial excess body fat. "Our work identified vascular dysfunction risk genes, including Sox17, Ulk4, Nbeal1, Cdkn1a and Plec, as obesity-regulated genes in the endothelium." (PMID 36400935, 2022). "Obesity led to the upregulation of Sox17 in lung art ECs, which, importantly, was mitigated by the reversion diet." (PMID 36400935, 2022).
oral cancer (1 paper, 2017). "In oral cancer, several genes related to WNT signaling are found silenced by DNA methylation, including SFRP (Secreted frizzled-related protein), SOX17 (SRY-box 17), and WIF1 (WNT inhibitory factor 1)." (PMID 28704968, 2017).
ovarian serous cystadenocarcinoma (1 paper, 2019). A malignant serous cystic epithelial neoplasm arising from the ovary. "MME, SOX17, AGTR1, PGR, and ESR1 had the highest amplifications frequency ranging from 4% to 11% in ovarian serous cystadenocarcinoma." (PMID 31879572, 2019).
pancreatic cancer (1 paper, 2021). "The key findings of the current study highlights ZNF804A, ZFP82, TRIM58, SOX17, and C12orf42 as hypermethylated/downregulated genes in pancreatic cancer associated with the development and progression of pancreatic cancer through their modulation of specific pathways." (PMID 33833773, 2021). "Univariate Cox model and Kaplan–Meier method revealed that, among 31 MeDEGs, 5 hypermethylated/downregulated genes (ZNF804A, ZFP82, TRIM58, SOX17, and C12orf42) were correlated with poor survival of patients with pancreatic cancer." (PMID 33833773, 2021). "Taken together, the key findings of the current study demonstrate that ZNF804A, ZFP82, TRIM58, SOX17, and C12orf42 are hypermethylated/downregulated genes in pancreatic cancer and may be associated, through their modulation of specific pathways, with unfavorable pancreatic cancer prognosis." (PMID 33833773, 2021). "In the current study, 5 hypermethylated/downregulated genes in pancreatic cancer were identified, including ZNF804A, ZFP82, TRIM58, SOX17, and C12orf42, all of which were found to be correlated with the poor survival of pancreatic cancer patients." (PMID 33833773, 2021).
papillary thyroid cancer (1 paper, 2019). "Downregulating TRIM30- in Sox17-overexpressing cancers may create new avenues for treating papillary thyroid cancer." (PMID 31823782, 2019).
prediabetes (1 paper, 2014). "Pancreatic loss of Sox17 resulted in trafficking defects of proinsulin through the ER, dilated and distended secretory organelles, and a trend of increased secretion of proinsulin, all of which are hallmarks of prediabetes." (PMID 25144761, 2014). "However, it is possible that factors that act downstream of Sox17 might be association with prediabetes." (PMID 25144761, 2014). "Our investigation of Sox17 regulated transcripts clearly indicates a central role for this factor in regulating insulin secretory pathways, and it is possible that some of these might be deranged in prediabetes in humans." (PMID 25144761, 2014).
premature ovarian failure (1 paper, 2023). "This study explores the relationship between SOX17 and the proliferation and differentiation of human germ cells, to provide a theoretical basis for the treatment of patients suffering from premature ovarian failure and patients with cancer needing ovarian fertility preservation." (PMID 37576970, 2023).
thyroid neoplasms (1 paper, 2026). "Notably, double-negative PAX8/SOX17 status completely excluded Müllerian origin in metastases from colorectal, breast, and pulmonary primary tumors (100% specificity), though renal (all PAX8+) and thyroid neoplasms (63.6% PAX8+) required additional markers for distinction." (PMID 41664069, 2026).
vesicoureteral reflux (1 paper, 2010). Abnormal flow of urine from the urinary bladder back into the ureters. "We have identified mutations in SOX17, an HMG-box transcription factor and Wnt signaling antagonist, in eight patients with CAKUT (seven vesico-ureteric reflux, one pelvic obstruction)." (PMID 20960469, 2010).
viral infection (1 paper, 2020). "To answer the question whether or not HPV infection results in a switch of SOX expression, we studied the association between the topographic localization of SOX17 and SOX2 expressing epithelia and the viral infection as detected by p16 and ISH, using 23 cases of SIL that could be studied in detail." (PMID 32644288, 2020).
Waardenburg syndrome type 2E (1 paper, 2023). Any Waardenburg syndrome type 2 in which the cause of the disease is a mutation in the SOX10 gene. "The HMG box position 58 had ClinVar variants in the SOX10 homologous SOXE member linked to pathogenic annotation for Waardenburg syndrome type 2E, and SOX17 was also associated with disease due to changes at this site." (PMID 36672963, 2023).
tumor (118 papers, 2009 to 2026). "SOX17 encodes a transcription factor involved in kidney development, oligodendrocyte differentiation, tumor cell–macrophage interactions, and negative regulation of the WNT signaling pathway." (PMID 41155038, 2025). "Sox17 expression is highest in more mature brain endothelial cells, suggesting that tumor-associated blood vessels in DMGs mainly consist of existing mature vasculature, and not newly created vessels that develop in a highly organized fashion." (PMID 34425907, 2021). "Together these data are consistent with SOX17 being under cancer specific mutational selection in this tumor type." (PMID 28978154, 2017). "SOX17 is a developmental transcription factor necessary for proper endoderm formation that has been implicated as a tumor suppressor and shown to modulate WNT signaling." (PMID 28978154, 2017). "The SOX17 mutation pattern we observed in EECs is consistent with that of a tumor suppressor, in which critical regions are perturbed through single amino acid substitutions, and nonsense and frameshift mutations occur throughout the entire coding sequence." (PMID 28978154, 2017). "SOX17 transcription is repressed in various solid tumors through epigenetic and other mechanisms, and it has been implicated as a tumor suppressor in EC." (PMID 28978154, 2017). "SOX17 methylation in tumor tissue is associated with poor prognosis in breast and esophageal cancer." (PMID 26764421, 2016). "Endothelial-specific deletion of sox17 in embryonic or perinatal mice causes defects in arterial differentiation and vascular formation and regulates endothelial cell proliferation, sprouting, and migration to promote tumor angiogenesis in adult mice." (PMID 37895315, 2023). "Among which, the hypermethylation of ZNF804A, ZFP82, TRIM58, SOX17, and C12orf42 were all noted to be significantly associated with tumor-related pathways, including calcium signaling pathways, neuroactive ligand-receptor interaction, glycosynthetic ganglion series and intercellular junctions." (PMID 33833773, 2021). "SOX17 mutation status was significantly associated with tumor grade." (PMID 28978154, 2017). "We also identified a significant association between SOX17 mutation status and tumor grade." (PMID 28978154, 2017). "To explore tumor stage‐associated genes, we discovered that the correlation of expression for PDGFRA and SOX17 in neighboring cells is higher in early‐stage tumor patients but not in late‐stage patients." (PMID 40420636, 2026). "Conversely, other SOX family members, such as SOX17, exhibit tumor-suppressive potential, underscoring the dual functionality within the SOX family." (PMID 41268614, 2026). "Functional studies showed that Sox17 overexpression in tECs drove aberrant tumor angiogenesis, whereas knockdown significantly delayed tumor progression by inhibiting pathological neovascularization and promoting vascular remodeling." (PMID 40919158, 2025). "In particular, the vascular normalization effect induced by Sox17 deletion was sustained, which not only enhanced the tumor infiltration efficiency of anticancer drugs, but also inhibited the formation of metastatic foci." (PMID 40919158, 2025). "In immunohistochemical staining, all YST‐like tumor tissues were focally positive for the YST markers SOX17 and FOXA2 and showed a YST‐like morphology in hematoxylin and eosin staining." (PMID 40025812, 2025). "the present study demonstrated that tumor endothelial cells (tECs) exhibit significant heterogeneous expression of Sox17, and its high expression level is specifically enriched in the VEGFR2 high-expression subpopulation." (PMID 40919158, 2025). "A heatmap based on log2-fold change values demonstrated general overexpression of Wnt pathway genes in cancers, except for genes such as CAMK2A, SFRP1, and SOX17, which were underexpressed in several tumor types." (PMID 40002717, 2025). "SOX17 inhibits tumor cells’ ability to sense and respond to IFNγ, thereby preventing anti-tumor T cell responses." (PMID 39889187, 2025).
tumor (continued). "This cluster was enriched in genes involved in differentiation and developmental processes (for example, SOX1 and SOX9, HOXD3 and HOXD8, and TBX4) and genes implicated as tumor suppressors (for example, SOX1 and SOX17, TSHZ3, WT1-AS, and FGF14)." (PMID 40931149, 2025). "These intricate biological processes underscore the SOX17's pivotal role in modulating tumor immune responses." (PMID 39279027, 2024). "Correlation of SOX17 expression in endothelial cells of tumor‐penetrating vessels with CD8+ T cells in the cancer stroma." (PMID 39385307, 2024). "Regarding SOX17 expression in cancer stroma niches, SOX17 immunoreactivity was found in endothelial cells of tumor‐penetrating vessels in 19 of 83 LUAD cases." (PMID 39385307, 2024). "Overexpression of Sox17 also promotes tumor angiogenesis and vascular abnormalities, while Sox17 deletion in ECs reduces tumor angiogenesis and normalized tumor vessels, inhibiting tumor growth." (PMID 36795082, 2024). "CRISPR-Cas9 was then used to knock out Sox17, revealing that SOX17 promotes an immunosuppressive environment and tumor progression by hindering immune clearance mechanisms." (PMID 39279027, 2024). "Summary of the clinicopathological characteristics of patients based on tumor endothelial SOX‐17 expression." (PMID 39385307, 2024). "SOX17 immunoreactivity was found in endothelial cells of tumor‐penetrating vessels in 19 of 83 tissue specimens." (PMID 39385307, 2024). "SOX17 overexpression acts as a tumor suppressor of cancer cell growth, proliferation, migration, and invasion." (PMID 36661515, 2023). "Several studies have reported the pivotal roles of SOX17 and its paralog, SOX7, in development and tumor angiogenesis, and SOX17 has been reported to display an endothelial cell-specific expression pattern." (PMID 37856473, 2023). "Results showed that the high value of regulatory potential between MFAP5 and some of its top predicted NOTCH1/WNT pathway target genes (CCND1, HES1, MYC, RBPJ, NOTCH1, CCN3, CTNNB1 and SOX17) in inferring signaling paths in tumour tissues." (PMID 36855786, 2023). "Notch intracellular domain overexpression downregulates SOX17 expression in primary endothelial cells, avoiding the excessive tip cell formation and hyperbranching of the vascular network during development and tumor angiogenesis." (PMID 36661515, 2023). "SOX17 in mice tumor endothelial cells promotes tumor progression, angiogenesis, and vascular destabilization." (PMID 36661515, 2023). "Further, to investigate the effect of SOX17/NRF2 pathway on tumor growth in vivo, KYSE510-R cells with manipulated protein expression were subcutaneously injected into BALB/c nude mice." (PMID 36310172, 2022). "In this study, the low expression of SOX17 was significantly correlated with tumor differentiation, depth of invasion, lymph node metastasis, and pTNM stage, suggesting that SOX17 acts as a tumor suppressor gene in ESCC." (PMID 36072972, 2022). "SOX17 protein expression showed inverse correlations with tumor size, grade of differentiation, depth of invasion, and pTNM stage." (PMID 36072972, 2022). "Xenograft mouse models were used to study the role of SOX17/NRF2 axis in tumor growth and the efficacy of carboxymethyl cellulose-coated zero-valent-iron (ZVI@CMC)." (PMID 36310172, 2022). "Consistent with in vitro cell behavior observations, SOX17 overexpression reduced the tumor growth while NRF2 overexpression promoted tumor growth as compared to the control." (PMID 36310172, 2022). "SOX17 gene promoter methylation can be used as a tumor suppressor and dysregulated oncogene in many tumors." (PMID 34557230, 2021). "Loss-of-function and gain-of-function studies have demonstrated that SOX17 in endothelial cells promotes tumor angiogenesis and the formation of vessel abnormalities." (PMID 34728626, 2021). "These suggest that ASMTL-AS1 is a tumor-inhibiting lncRNA that regulates the miR-1228-3p/SOX17/β-catenin axis in vivo, which was in line with in vitro and clinical data." (PMID 34006305, 2021).